RNU4-38P (RNA, U4 small nuclear 38, pseudogene)
Gene: Small nuclear RNA gene on chromosome 3 (170,057,301 to 170,057,429, forward strand). Ensembl gene ENSG00000201342.
Homologues: Orthologues: chimpanzee U4 (100% identical), rabbit U4 (56% identical), guinea pig U4 (50% identical), guinea pig U4 (49% identical), pig U4 (49% identical), dog U4 (47% identical). Paralogues in human: RNU4-67P (73% identical), RNU4-80P (73% identical), RNU4-13P (72% identical), RNU4-84P (72% identical), RNU4-44P (71% identical), RNU4-7P (70% identical), RNU4-16P (68% identical), RNU4-20P (68% identical), RNU4-31P (68% identical), RNU4-68P (68% identical), RNU4-12P (67% identical), RNU4-23P (67% identical), and 81 more.